CD4 (CD4 molecule)
Diseases named in the same sentence as CD4 in open-access papers (continued):
Sharing a sentence is not in itself a finding about the gene and the disease.
tumor (continued). "Although interactions with CD4+ and CD8+ T cells can also induce DC activation, the main topics of this review are cDCs and pDCs, their functions in tumor immunity, and the ways in which they activate the innate immune system." (PMID 38512518, 2024). "To comprehensively characterize tumor antigen-specific CD8+ and CD4+ T-cell responses, we first generated an OVA-protein transduced D4M cell line." (PMID 38631706, 2024). "The TME contains chemicals such tumor antigens, IL-2, IL-10, TGF-β, and other soluble molecules that stimulate the T-cell receptor (TCR) and enhance the transformation of naive CD4+ T-cells into iTregs." (PMID 38509593, 2024). "Phenotypic analysis of the cultures demonstrated that CD8 T cells were preferentially expanded by tumor cell-loaded autologous IFN-DC, with the exception of MBR-4 and PBR-14, which exhibited an outgrowth of CD4 T cells." (PMID 39340087, 2024). "Conversely, regulatory T cells, a suppressive subset of CD4+ T lymphocytes, can inhibit immune responses initiated by CD8+ cytotoxic T lymphocytes, thereby promoting tumor evasion." (PMID 39091612, 2024). "We subsequently analyzed the scores for CD3+, CD4+, CD8+, and FoxP3+ cells localizing either at the inner area of the tumor (In area) or at the tumor periphery (P area) (see the Materials and Methods section for details)." (PMID 38891095, 2024). "PD-1 blockade has been shown to reinvigorate and expand exhausted tumor-reactive PD-1+ CD8 T cells and CTLA-4 blockade to promote T cell priming, clonal expansion, and CD4 and CD8 T cell trafficking into immunologically cold tumors." (PMID 39190534, 2024). "Results showed that COL4A1 was negatively correlated with tumor purity, and positively correlated with CD8 + T cell, dendritic cell, macrophage, neutrophil, and CD4 + T-cell infiltration." (PMID 38907304, 2024). "We implemented the scATOMIC to annotate single cells to five cell types (B cell, CD4 T cell, CD8 T cell, macrophage and tumor cells) for downstream analysis." (PMID 39563471, 2024). "This was accompanied by a dose-associated statistically significant on-target reduction of PD-1 surface protein in tumor CD45+ leukocytes, including CD4+ and CD8+ T cells, for mice treated with PH-762." (PMID 39697325, 2024). "This correlated with a significantly higher number of CD4+ and CD8+ T cells within the tumor micro-environment in the combined therapy compared to both sham and sham + anti-PD-1 treatment groups." (PMID 38954031, 2024). "Further experiments of adoptive cell transfer or in vivo cell depletion show that both CD4+ and CD8+ T lymphocytes prove fundamental in tumor rejection." (PMID 39035008, 2024). "Next, we investigated the frequencies of tumor-infiltrating lymphocytes, given the observations that CD73 inhibits CD8+ T and NK cells while upregulating CD4+ regulatory T cell activities." (PMID 38601156, 2024). "The depletion of CAFs by ProAgio consequentially decreases tumor immunosuppressive effects, e.g., an increase in CD8+ T-cells and a decrease in CD4+ Treg cells and MDSCs in lung tumors." (PMID 39001545, 2024). "This formulation elicited superior CD4+ and CD8+ T-cell responses and significantly enhanced IFN-γ production, resulting in a substantial reduction in tumor growth and an increase in lifespan compared to other formulations." (PMID 39204073, 2024). "used the functional intravital image to find that anti-CD19+ CD4+ CAR-T cells mainly derived IFN-γ that diffuses in the TME and directly acts on tumor cells in treatment-responsive B-cell lymphoma." (PMID 39372416, 2024). "The addition of 2-DG to the TCM from infected tumours was able to enhance the arrested TCR signalling even further (p < 0.01, CD4 and CD8 stimulated: vehicle vs 20 mM 2-DG)." (PMID 39558103, 2024). "ssGSEA scores for activated CD4+T cells and the immunosuppressive Th2 cells were significantly increased in TCGA LUAD tumor tissues with high TIMELESS expression vs. low TIMELESS expression." (PMID 38261568, 2024).
tumor (continued). "In contrast, CD4 + and CD8 + T cells play a crucial role in anti-tumor immunity and help change the tumor microenvironment into a more tumor-suppressive condition." (PMID 38627864, 2024). "The proportion of CD8+ T cells, CD4+ T cells, or NK cells (CD3–/CD56+) was significantly lower in MLiM than in CLiM or PLiM tumour areas." (PMID 39496484, 2024). "Tregs have been identified as a pro-tumor subpopulation of CD4+ T cells in GBM tumor tissues and the circulatory system, which can direct cytotoxic T lymphocytes (CTLs) by suppressing tumor cell immune responses." (PMID 39175478, 2024). "As expected, we found that the number of CD4+ and CD8+ T cells increased significantly in the Scu-treated mice, indicating that Scu increased T-cell infiltration in the tumor." (PMID 38622131, 2024). "Huang and colleagues (2020) found a strong positive correlation between the gene expression of CXCL10 and the infiltration into the tumor of immune cells (B cells, CD8+ T cells, CD4+ T cells, macrophages, neutrophils, dendritic cells)." (PMID 39339213, 2024). "This activation leads to the recruitment of CD4+ and CD8+ T lymphocytes within the tumor microenvironment." (PMID 38892423, 2024). "Lymphocytes, on the other hand, suppress tumor formation, and mediate the antitumor effects of CD8+ and CD4+ T cells in the tumor microenvironment." (PMID 39596977, 2024). "These natural products have been shown to downregulate the percentages of immunosuppressive cells, such as MDSCs, Tregs, and M2-MACs, while promoting the proportions and function of anti-tumor effector T cells like CD8+ T cells, CD4+ T cells, and NK cells." (PMID 38444857, 2024). "The number of the CD3, CD4, CD8 and CD20 positive cells were significantly lower in the tumor compared to the peritumoral cirrhotic parenchyma (p<0.05)." (PMID 38265097, 2024). "We discovered that increased SCD in CD4+ T cells promotes Th1 cell polarization and activation of the cytotoxic effect in CD8+ T cells within the tumor immune microenvironment." (PMID 39543650, 2024). "We validated these flow cytometry results by immunohistochemical analysis, which demonstrated a consistently augmented infiltration of CD3+, CD4+, and CD8+ T cells within the tumor after siGsdmc treatment." (PMID 39297408, 2024). "treated osteosarcoma with L19TNF-a (L), marfalan (M), and gemcitabine (G) showed a decrease in Treg cells, myeloid suppressor cells (MDSCs), and a significant increase in CD4+ and CD8+ T cells in tumor tissue." (PMID 39916962, 2024). "The amounts of tumor-infiltrating CD8+ and CD4+ TCR-T were both higher in mice receiving IL-21R-TCR-T than conventional TCR-T, especially in the CD8+ TCR-T subsets with an approximately ten-fold increase in mice receiving IL-21R-TCR-T treatment." (PMID 38643203, 2024). "CD8+ and CD4+ T cells receive signals along the MHC-I and MHC-II pathways respectively, from macrophages and presumably due to direct interactions with tumor cells." (PMID 38358352, 2024). "Several studies have also found that the synergistic effect of CD4+ T cells and CD8+ T cells in the anti-tumour immune response extends to CAR-T cell adoptive immunotherapy." (PMID 38475858, 2024). "Further exploration into the mechanism of inhibitory effects was conducted through the immunofluorescence staining of CD3+CD4+ and CD3+CD8+ T cells infiltrating in distant tumor tissues." (PMID 39494618, 2024). "The anti-tumor efficacy of ImmAct was found to be critically dependent on CD8+ T cells, even though it was partially dependent on CD4+ T cells and B cells." (PMID 38675737, 2024). "A marginal significant correlation was found between baseline low level of CD4 + CD25 + cells and distant tumor response (P = 0.078)." (PMID 38430269, 2024). "OTX008 treatment significantly increased tumor-infiltrating CD8+ and CD4+ T cell populations, whereas the proportion of intratumoral Tregs among the CD4+ T cell population were markedly reduced." (PMID 38169569, 2024).
tumor (continued). "Further experiments of adoptive cell transfer or in vivo cell depletion showed that both CD4+ and CD8+ T lymphocytes prove fundamental in tumor rejection." (PMID 39035008, 2024). "In order to determine how the increase in antigen-presenting cells activated the T-cells, the abundance of CD4 + and CD8 + T-cells in tumor tissues and spleen was investigated." (PMID 39010088, 2024). "DCs excite CD4+ and CD8+ TILs in the lymph nodes, followed by TIL-Bs initiating recall responses in the tumor." (PMID 39671359, 2024). "There was also a significant decrease in CD3e+PD-1+, CD8a+PD-1+, and CD4+PD-1+ T cells, as well as CD45+ cells in post- versus pre-ICI tumor samples (P < .05)." (PMID 38207230, 2024). "Beyond the anti-tumor potential for CD8+ T cells, the role for CD4+ T cells includes support of CD8+ T cell activation and direct cytotoxic activity." (PMID 38195752, 2024). "Our data showed that the TLS density was significantly positively correlated with CD4+ T cells, CD8+ T cells, CD20+ B cells and CD45RO+ memory T cells and negatively correlated with CD15+ TANs in the tumor margin." (PMID 38322490, 2024). "In comparison, LNP-I-V induced the infiltration of CD4+ and CD8+ T cells in the tumor tissues, revealing that the stimulating anti-tumor immunity ability of co-delivering oligonucleotides and chemotherapeutic drugs by LNP." (PMID 38675231, 2024). "Published studies with experimental mouse tumor models as well as CAR-T cell therapies in patients provide compelling evidence supporting a critical role for CD4+ T cells in tumor regression." (PMID 39287991, 2024). "They stimulate antitumor responses of CD4+ T cells and indirectly support the function of CD8+ T cells in the tumor microenvironment." (PMID 38540312, 2024). "In the tumor microenvironment, anti-PD-L1 increased CD3+ T, CD4+ T, and CD8+ T cells and M1 macrophages." (PMID 38540311, 2024). "After completion of vaccine treatments, a significant induction of CD4+ and CD8+ T-cells was appreciated as well as effective immunotherapy-induced tumor regression either alone or in combination with a PD-1 inhibitor." (PMID 39682188, 2024). "While both conventional CD4 and CD8 T cells drive immunotherapeutic responses to cancer, CD8 T cells are often the most potent direct inducers of tumor cell death." (PMID 38187708, 2024). "The absence of SENP3 expression in DCs abrogates IFN-I responses, and the low frequency of IFN-γ-expressing CD4+ and CD8+ effector T cells in the tumor and draining lymphoid nodes results in poor anti-tumor activity." (PMID 38280996, 2024). "The primed and activated CD4+ and CD8+ T cells are trafficked into the tumor to exert their effector functions, thus making immunologically cold tumors hot." (PMID 39845957, 2024). "In particular, CD3+ CD4+ T cells seem to be mainly located in the stromal tissue (inset), whereas CD3+ CD8+ T cells are more prone to infiltrate the tumor (inset)." (PMID 38338669, 2024). "Whereas, in the established subcutaneous transplantation tumor model, IL-17 also exhibits anti-tumor activities by enhancing NK cell and CTL cell activation and by recruiting neutrophil, NK cell, CD4+, and CD8+ T cell into the TME." (PMID 39906741, 2024). "PD-L1 IC ≥1% was more often seen in tumours with high CD4+ T cells infiltration (p = 0.02), while PD-L1 CPS ≥1%—in tumours with high CD4+ and CD8+ T cells infiltration (p = 0.021 and p = 0.048, respectively)." (PMID 38541208, 2024). "Tregs are well known to suppress the anti-tumor activity of CD8+ T cells, CD4+ T cells, and other cytotoxic immune cells." (PMID 38538574, 2024). "Another limitation is the limited subset of immune cells (CD8+, CD4+ and CD20+ cells) that were analyzed using immunohistochemical staining of the tumor tissue." (PMID 38539483, 2024). "mIF on FFPE samples with antibodies of CD4, CD8α, FOXP3, Granzyme B, and pan CK were applied to analyze the tumor regions of pre- and post-ipilimumab treatment for 4 patients (P6, P7, P4 and P8)." (PMID 38448521, 2024).
tumor (continued). "Using a seven-color multiplex immunohistochemistry panel we identified tumor cells, CD163+macrophages, B cells, CD8+T cells, CD4+T helper cells and regulatory T cells (Tregs) in treatment-naive surgical resection specimens (n=29) and biopsies (n=18)." (PMID 39053947, 2024). "This was evidenced by significant increases in CD3+, CD4+, CD4+/CD8+ T cell subsets, and NK cell levels, suggesting an enhanced anti-tumor response from CD8+ T cells." (PMID 39906672, 2024). "To our knowledge, we are the first who evaluated PD-L1+ lymphocyte distribution in tumour tissue in the context of the TME (CD4+ T cells, Foxp3+CD4+ T cells, IL17A+CD4+ T cells, CD8+ T cells, M1 and M2 macrophages)." (PMID 39409156, 2024). "We next assessed the ability of TCR135-engineered mixed CD4+ and CD8+ T cells (TCR135-T cells) to kill tumor cells." (PMID 38412034, 2024). "Mechanistically, our study showed that mIL12 significantly enhanced the infiltration of CD4+ T cells, CD8+ T cells, cDC1, and CD103+cDC1 cells into the tumor microenvironment." (PMID 39584994, 2024). "Specifically, there was an increased infiltration of CD4+ and CD8+ T cells in tumor tissue, indicating enhanced anti-tumor immune activation." (PMID 39613774, 2024). "The prognostic impact of CD3, CD4 and CD8 were further analyzed based on tumor stage (early or advanced)." (PMID 38926643, 2024). "CD4+ TH17 cells promote antimicrobial inflammation, whereas regulatory T cells (Tregs) suppress anti-tumor immune responses, with their reduction potentially leading to metastatic regression in certain cancers." (PMID 39765634, 2024). "We also investigated the spatial intratumoural immune infiltration patterns (topography) of CD4+ and CD8+ T cells using multiplex IHC, which demonstrated a pronounced accumulation of CD4+ and CD8+ T cells in the core of WBM‐treated tumours." (PMID 39390760, 2024). "According to present knowledge, the ideal composition of TCR-T in terms of CTX CD4+ and CD8+ T cell presence and ratio remains questionable and is likely to differ according to either the MHC context or evaluated tumor model, regarding efficiency indicators." (PMID 38545119, 2024). "The results demonstrated that the combination of anti-IL-16 antibodies with MLN8237 results in decreased tumor growth, augmented infiltration of CD8+ T cells, and reduced infiltration of CD4+ T cells." (PMID 38291041, 2024). "Further, analysis of the anti-tumor cytotoxicity (E:T ratio 20:1) of CD8+ and CD4+T cells demonstrated a 3.9- and 6.8-fold increased response (respectively) following combinatorial treatment of anti-CTLA4 mAb with anti-TGFβ mAb, compared to isotype treatment." (PMID 38891044, 2024). "We saw a shift towards more CD4+ Th and less CD8+ Tc in the tumor core compared to the tumor margin." (PMID 38566984, 2024). "When found in the tumor microenvironment, they play a critical role in the release of chemo-attractive cytokines resulting in the tumor infiltration of other adaptive (such as CD8 and CD4 T cells) immune cells." (PMID 38397152, 2024). "Eight major cell types, including HCC, B cells, macrophages, fibroblasts, endothelial cells, mast cells, CD4+ T cells, and CD8+ T cells, were identified in the tumor samples." (PMID 38577593, 2024). "Univariate analysis was conducted to assess the contribution of various factors (including IL-38, CD4, CD8, PD-1, sex, age, CRC location, tumour size, differentiation, depth of invasion, metastasis, and TNM staging) to the prediction of survival rates." (PMID 38533512, 2024). "Similar results were also observed when tumor cell-derived culture media was used on macrophages (p < 0.001) and Peripheral Blood Mononuclear Cells (PBMC)-derived human CD4 + T cells (p = 0.0025)." (PMID 39616302, 2024). "We performed immunofluorescence staining on tumor samples from both LCC and RCC, using lymphocyte markers CD4 and CD8, along with the exhaustion marker PD1." (PMID 39267963, 2024).
tumor (continued). "(F–I) The protein expression of CD4, CD8, CD86, and Granzyme in tumor tissues is detected by Western blot." (PMID 38441416, 2024). "Ideally, antigen-specific CD8+ and CD4+ T cells respond, respectively, to MHC-I and MHC-II cell surface complexes on cancer cells, activating host immune mechanisms that target the tumor for removal." (PMID 38915093, 2024). "We discovered that anlotinib triggers a significant influx of both CD4+ and CD8+ T cells to tumour locations, which is mediated by the release of inflammatory cytokines and chemokines." (PMID 39095323, 2024). "Subsequently, we examined the infiltration of CD4 + T cells, CD8 + T cells, DCs, and NKs within the tumor tissues using flow cytometry." (PMID 38600588, 2024). "The activation marker CD44 was highly expressed in tumor-infiltrating CD8+ and CD4+ T cells, but CD8+ T cells in KO tumors expressed significantly lower levels of CD44 than did those in WT tumors." (PMID 38618956, 2024). "Our study revealed significantly lower intratumoral CD4 + T cell density and lower intratumoral CD4/CD8 ratio in primary tumor after neoadjuvant therapy (respectively, 0.012 and 0.016)." (PMID 38468248, 2024). "The increased number of CD4+ Treg and reduced CD8+ anti-tumor responses indicate the prevalent pro-tumor mechanisms in the TME, and more research is needed to uncover these biological processes." (PMID 39075108, 2024). "In contrast, when either CD4 or CD8 T cells were depleted, tumour progression occurred similarly in both Fgl2WT and Fgl2−/− mice." (PMID 38191799, 2024). "High TIL and its subset (CD4+, CD8+, CD56+, CD57+, GNLY+, and GZMB+ TIL) infiltration correlated with favorable clinicopathological features of tumor." (PMID 39643914, 2024). "In most patients enhanced immune activation in peripheral CD4+ and CD8+ T cells was observed and 4 out of 17 patients displayed expansion of putative tumour reactive CD103+CD39+CD8+ TILs." (PMID 38440738, 2024). "In line with the idea that CCL19 supports immune surveillance, the administration of intratumoral CCL19 mobilized CD4+ and CD8+ T cells and DCs at the tumor." (PMID 38786066, 2024). "The presence of certain cell types, such as tumor antigen-specific CD8+ T cells and CD4+ regulatory T cells, are critical cellular elements to sustain or impair anti-tumor immune responses, respectively." (PMID 38464315, 2024). "In tumor‐draining lymph nodes, there was a decrease in CD8+ T cells in cGAS−/− mice, along with reduced CD8+ and CD4+ TCM‐like cells, increased naive cells, and a significant decrease in Tfh cells." (PMID 38900071, 2024). "Although CD4 T cells and MHC-II neoAgs are critical components of anti-tumor immunity, we chose to utilize an SLP vaccine against a single MHC-I neoAg to definitively link the MHC-I neoAg vaccine response to a specific defined neoAg." (PMID 39446585, 2024). "TIGIT is extensively overexpressed on tumor-infiltrating lymphocytes (TILs) such as CD8+ T cells, CD4+ T cells, regulatory T cells (Tregs), and natural killer (NK) cells across various malignancies." (PMID 38229100, 2024). "According to the study, in patients who had a better survival, tumor samples exhibited a greater percentage of CD8+ T cells, but a lesser percentage of CD4+ T cells compared to tumor samples from patients with a short survival." (PMID 38835055, 2024). "Tumor-infiltrating lymphocytes (TILs) are increasingly recognized for their role in TNBC prognosis, and TME remodeling (recruitment of CD4+ T cells, CD8+ T cells, and NK cells) can enhance the efficacy of immunotherapy." (PMID 39867909, 2024). "Regulatory T cells, identified by the expression of CD4, CD25, and Foxp3 proteins, play a pivotal role in tumor progression by suppressing immune responses specifically targeting tumors." (PMID 38817895, 2024). "COL4A3/4 was negatively correlated with tumor purity while positively correlated with CD8 + T cells, B cells, dendritic cells, macrophages, neutrophils, and CD4 + T cell infiltration." (PMID 38907304, 2024).